RN7SKP153 (RN7SK pseudogene 153)
Gene: Miscellaneous RNA gene on chromosome 8 (119,711,830 to 119,712,145, reverse strand). Ensembl gene ENSG00000201896.
Homologues: Orthologues: chimpanzee 7SK (98% identical). Paralogues in human: RN7SKP180 (75% identical), 7SK (75% identical), RN7SKP79 (75% identical), RN7SKP47 (74% identical), RN7SKP71 (74% identical), RN7SKP124 (73% identical), RN7SKP176 (73% identical), RN7SKP189 (73% identical), RN7SKP78 (73% identical), RN7SKP173 (73% identical), RN7SKP203 (73% identical), RN7SKP243 (73% identical), and 284 more.